CGAS (cyclic GMP-AMP synthase)
Diseases named in the same sentence as CGAS in open-access papers (continued):
Sharing a sentence is not in itself a finding about the gene and the disease.
bladder cancer (10 papers, 2022 to 2026). "Thus, DCs may play an important role in cisplatin-related cGAS-STING immune effects in bladder cancer, although their underlying mechanism and specific functions in the tumor microenvironment remain to be clarified." (PMID 36230972, 2022). "Cisplatin inhibits the proliferation of bladder cancer through enhancing accumulation of dsDNA to activate cGAS-STING signal in bladder cancer." (PMID 40552295, 2025). "It has been demonstrated that cisplatin can enhance the recognition of chromatin in cancer cells by the cGAS protein, which in turn activates the signaling pathway and exerts an inhibitory effect on the proliferation of bladder cancer cells." (PMID 39601590, 2025). "For instance, cGAS-STING signaling amplifies the immune response induced by cisplatin in patients with bladder cancer." (PMID 38139802, 2023). "Cisplatin induced cGAS-STING signal inhibited the proliferation of bladder cancer and increased the infiltration percentages of CD8+ T cells and dendritic cells in a transplantation mice tumor model." (PMID 36230972, 2022). "We found cisplatin induced immune response in bladder cancer by RNA sequencing and validated that cGAS-STING signal was deeply involved in this response." (PMID 36230972, 2022). "CSG-3 signature metastatic bladder cancer, characterized by highly expressed genes important for functional cGAS–STING activation, has the highest overall level of tumor-infiltrating leukocytes and is consequently associated with better overall survival with regard to immunotherapy." (PMID 37444620, 2023). "Bacillus Calmette–Guérin (BCG) immunotherapy for the treatment of bladder cancer (BC) depends on the recognition of bacteria by extracellular toll-like receptors (TLRs) or the detection of mycobacterial DNA by endosomal TLRs or the cGAS-STING pathway." (PMID 40778061, 2023). "In summary, our findings indicated a cisplatin dependent cGAS-STING signal in bladder cancer." (PMID 36230972, 2022). "Urinary tract tumors, including bladder cancer, show relatively high expression of cGAS." (PMID 36230972, 2022). "Since cisplatin activates cGAS-STING signaling in bladder cancer cell lines, the role of cGAS-STING in bladder cancer progression remains unclear." (PMID 36230972, 2022). "We found that cisplatin treatment induces cGAS-STING-dependent immune responses in bladder cancers." (PMID 36230972, 2022). "We found that the transcription levels of CCL20 and CXCL14 in T24 and TCCSUP cells were significantly increased in the cisplatin treatment groups, and the correlation analysis showed that CCL20 and CXCL14 were significantly correlated with the cGAS-STING signal in the TCGA bladder cancer cohort." (PMID 36230972, 2022). "Importantly, in an independent bladder cancer immunotherapy-treated cohort, patients with low cGAS-STING expression showed limited response to treatment, while patients with high expression showed improved response and prognosis, particularly among patients with high CIN and more neoantigens." (PMID 36923311, 2022). "A2 specifically binds to the Lys73 site of MAD2L1, activating the cGAS‐STING pathway and thereby inducing apoptosis in bladder cancer cells." (PMID 41168906, 2026). "The activation of cGAS-STING can lead to the degradation of β-catenin, allowing for enhanced immune responses against bladder cancer." (PMID 38240703, 2024). "In a mouse xenograft tumor model, induction of cGAS-STING signaling by cisplatin enhanced CD8+ T-cell and dendritic cell infiltration and thus reduced bladder cancer cell growth." (PMID 38139802, 2023).
bladder cancer (continued). "The prognostic significance and immunological role of cGAS-STING pathway-related genes (CRGs) in individuals diagnosed with bladder cancer (BLCA) have not yet been fully elucidated." (PMID 38240703, 2024). "This signal could be enhanced by accumulation of dsDNA and chromatin dissociated cGAS and would finally recruit infiltration DCs and CD8+ T cells in bladder cancer tumor microenvironment." (PMID 36230972, 2022). "In order to ascertain whether the expression of four genes was influenced by the state of the cGAS-STING pathway, we employed varying concentrations of ADU-S100 (a cGAS-STING pathway agonist) to treat the T24 bladder cancer cell line, thereby inducing alterations in their expression levels." (PMID 38240703, 2024). "The specific role of POLR3G in the context of cGAS-STING activation and bladder cancer is not well-established, and further research is needed to elucidate its significance." (PMID 38240703, 2024).
depression (10 papers, 2022 to 2026). "Therefore, the present study proposed a hypothesis that the potential molecular mechanism of EA in the treatment of depression in rats is associated with the regulation of the CGAS-STING-NLRP3 signal axis." (PMID 38643466, 2024). "Neuroinflammation via the cyclic GMP-AMP synthase (cGAS)–stimulator of interferon genes (STING) pathway and reduced hippocampal brain-derived neurotrophic factor (BDNF) expression are key mechanisms underlying stress-induced depression." (PMID 41226472, 2025). "Interestingly, fluvoxamine, a commonly used medication for treating anxiety and depression, exhibits anti-fibrotic effects by inhibiting the cyclic GMP-AMP synthase-stimulator of interferon genes (cGAS-STING) pathway and related signaling pathways, making it a potential effective treatment for IPF." (PMID 40655156, 2025). "The cGAS-STING signaling axis may be a promising target for the treatment of depression." (PMID 38643466, 2024). "This dual function positions the cGAS-STING pathway as a potential link between immune dysregulation and the neurobiological foundations of depression." (PMID 40660450, 2025). "While our data suggested that RU-521, cGAS/STING pathway inhibitor, ameliorated SNL-induced hypersensitivity and depression." (PMID 35645765, 2022). "By inhibiting the cGAS-STING pathway, exercise reduces the expression of interferon beta-1 (IFNβ1) and other pro-inflammatory cytokines IL-6 and TNF-α, thereby decreasing the inflammatory response, improving mitochondrial function, and alleviating depression." (PMID 40699781, 2025). "In summary, exercise regulates signaling pathways such as NF-κB, NLRP3, UCP2, and cGAS-STING, reduces the release of mtDNA and pro-inflammatory factors, inhibits the inflammatory response, and decreases ROS production, thereby improving mitochondrial function and alleviating depression." (PMID 40699781, 2025). "Furthermore, the sustained activation of the cGAS-STING pathway can also increase the production of ROS, leading to more mtDNA release, which further drives the secretion of IL-1β and IL-18 and affects ATP synthesis, impacting mitochondrial energy metabolism and mediating the onset of depression." (PMID 40699781, 2025). "However, the role of cGAS-STING signaling axis in depression has not been clarified." (PMID 38643466, 2024).
diabetic kidney disease (10 papers, 2021 to 2026). Progressive kidney disorder caused by vascular damage to the glomerular capillaries, in patients with diabetes mellitus. "Experimental models of diabetic kidney disease and Alport syndrome have shown that the cGAS-STING pathway plays a significant role in the development and progression of glomerular damage by regulating inflammation." (PMID 37958859, 2023). "Abnormal mitochondrial metabolism has a major role in diabetic nephropathy, and the cGAS–STING pathway has been confirmed to be activated by abnormal mitochondrial function." (PMID 34906241, 2021). "Additionally, activation of the cGAS-STING pathway has been observed in diabetic kidney disease resulting from mitochondrial damage." (PMID 37958859, 2023). "Therefore, we can speculate that the cGAS–STING signaling pathway may participate in the pathogenesis of diabetic nephropathy, and the exploration of this mechanism may helpelucidate the pathophysiology of diabetic nephropathy." (PMID 34906241, 2021).
osteosarcoma (10 papers, 2020 to 2025). A usually aggressive malignant bone-forming mesenchymal neoplasm, predominantly affecting adolescents and young adults. "This review provides an overview of cGAS/STING signalling, its divergent roles in the context of cancer, and collates current research which activates cGAS/STING as an adjuvant immunomodulatory target for the treatment of osteosarcoma." (PMID 39403376, 2024). "Emerging research demonstrates an immunostimulatory role for the cGAS/STING pathway in osteosarcoma, typically considered an immune-cold or immunosuppressed cancer type." (PMID 39403376, 2024). "We show that the ATR inhibitors VE822 and AZD6738 can potentiate radiation-induced, cGAS-dependent type I interferon signaling in several cell lines from human osteosarcoma and NSCLC." (PMID 36387237, 2022). "cGAS–STING/type I interferon pathway activation by OVs in osteosarcoma." (PMID 41451200, 2025). "Additionally, previous studies have demonstrated the expression of RIG-I in fibroblasts and the murine osteoblast cell line, MC3T3-E, at the level of mRNA, and the expression of cGAS in human osteosarcoma cells." (PMID 40135931, 2025). "This study highlights the need for STING signalling in chemokine expression following DNA damage and reveals variations in cGAS/STING components among osteosarcoma cell lines, which may impact patient responses to radiotherapy." (PMID 39403376, 2024). "However, despite its potential for tumorigenesis, the cGAS/STING pathway is being explored as a novel immunological target for osteosarcoma due to its vital anti-tumour inflammatory effects." (PMID 39403376, 2024). "The binding of cGAS to DNA slows replication forks via a STING-independent mechanism and cGAS deficiency accelerates fork replication but compromises fork stability, leading to increased sensitive to radiation and chemotherapy in U2OS cells, a human osteosarcoma epithelial cell line." (PMID 34374004, 2022). "A recent study has shown that ZNF598 regulates cGAS activation in U2OS cells, the human osteosarcoma cell line via modulating ribosome collision and translation stress." (PMID 40337520, 2025). "Reports indicate cGAS/STING dysregulation at various levels in a variety of cancers, including osteosarcoma, elucidated using in vitro models." (PMID 39403376, 2024). "For example, it is known that the primordial function of cGAS-STING signaling is the activation of autophagy to clear cytosolic DNA, and it has been reported that autophagy can remove micronuclei in osteosarcoma cells." (PMID 38867360, 2024). "Given the variable expression of cGAS/STING components and high chromosomal instability in osteosarcoma, some tumour subpopulations may activate NF-κB through non-canonical STING pathways, driving malignant progression even after cytotoxic treatment." (PMID 39403376, 2024).
chronic obstructive pulmonary disease (9 papers, 2021 to 2025). A chronic and progressive lung disorder characterized by the loss of elasticity of the bronchial tree and the air sacs, destruction of the air sacs wall, thickening of the bronchial wall, and mucous accumulation in the bronchial tree. "Chronic ozone exposure, which mimics smoke-induced chronic obstructive pulmonary disease (COPD) and induces reactive oxygen species (ROS) and mitochondrial damage, may also be associated with the cGAS-STING signaling in humans." (PMID 34381828, 2021). "The CGAS-deficient (Mb21d1–/–) mice do not show a discernible phenotype and survive normally without evidence of cardiac dysfunction, cardiac arrhythmias, myocardial fibrosis, or cell death." (PMID 40608429, 2025). "Recently, evidence showed that the cGAS-STING pathway over-activation is involved in multiple inflammatory lung diseases including cystic fibrosis, chronic obstructive pulmonary disease (COPD), idiopathic pulmonary fibrosis (IPF), asthma and COVID-19." (PMID 36982193, 2023). "Aberrant cGAS/STING activation might also play a role in diseases such as nonalcoholic steatohepatitis (NASH) and chronic obstructive pulmonary disease (COPD); nevertheless, this still requires further evaluation." (PMID 35406723, 2022).
Hypertension (9 papers, 2022 to 2025). The presence of chronic increased pressure in the systemic arterial system. "Additionally, whether the activation of the cGAS-STING pathway is closely associated with tissue damage beyond the myocardium in the context of hypertension remains to be determined." (PMID 37915571, 2023). "Paradoxically, in hypertension, mtDNA released from microglial mitochondria in the paraventricular nucleus activates cGAS, which in this context blocks autophagic flux and promotes neuroinflammation, sympathetic overdrive, and hypertensive cardiac injury." (PMID 41009042, 2025). "These suggest that the cGAS-STING pathway is directly involved in the development of Ang II-induced hypertension, which ultimately results in damage to peripheral tissues." (PMID 37915571, 2023). "In hypertension-induced myocardial injury, cGAS participates in neuroinflammation by impairing autophagy flux and inducing the pro-inflammatory phenotype of microglia, leading to sympathetic overactivation in hypertension and further causing myocardial injury in hypertension." (PMID 38643466, 2024). "have also shown that deletion of the cytosolic DNA sensor cGAS contributes to cardiac pathology in mice with pressure overload-induced hypertension but downstream signaling events responsible for cardiac pathology were not investigated; cGAS can have both STING-dependent and independent effects." (PMID 36483558, 2022).
injury (9 papers, 2020 to 2025). Damage inflicted on the body as the direct or indirect result of an external force, with or without disruption of structural continuity. "First, they used the selective cGAS inhibitor RU.521 in a mouse model of cerebral ischemia-reperfusion injury, which alleviated oxidative stress, NCOA4-mediated ferritinophagy, apoptosis, and infarct volume associated with CIRI." (PMID 39741707, 2024). "Taken together, activation of cGAS-STING participated in the pathophysiological process of LPS-induced acute lung injury, and pharmacological blockade of cGAS-STING conferred protection against ALI." (PMID 36982193, 2023). "In conclusion, our findings established a pivotal role for IL-33/ST2 in regulating the activation of cGAS/STING in APAP-induced liver injury." (PMID 37081450, 2023). "A recent RNA-seq analysis between young and aged traumatic brain injury mice reported age-related upregulation of cGAS and type I IFN, which appears to be closely related with microglia-mediated neuroinflammation." (PMID 35677585, 2022). "Furthermore, cGAS‐STING has been shown to enhance NLRP3 inflammasome activation in models of acute liver injury, indicating a potential mechanistic link in SCI." (PMID 40522023, 2025). "In summary, we conjecture that NETs might be involved in the regulation of inflammatory injury through the cGAS-STING pathway in acute lung injury." (PMID 36982193, 2023). "In this study, we uncovered the over-activation of the cGAS-STING pathway in LPS-induced ALI, while administration of H-151 successfully alleviated inflammatory lung injury." (PMID 36982193, 2023). "Together, these results indicate that the cGAS-STING pathway is involved in I/R-induced neuroinflammation and brain injury, and deletion of cGAS in microglia can attenuate I/R-induced brain injury." (PMID 32863951, 2020). "Activation of cGAS-STING signaling pathway, as evidenced by the increased expression of cGAS, STING, NF-κB, IL-1β, IFN-I TGF-β1, and collagen type I, has been observed in GMWCNT-induced lung injury." (PMID 37965345, 2023).
multiple myeloma (9 papers, 2016 to 2025). "We found that chemotherapeutic drugs such as melphalan and bortezomib cause DNA damage in myeloma cells, which activates the cGAS/STING signaling pathway." (PMID 40135791, 2025). "We further analyzed primary myeloma cells from 20 treated patients and found a positive correlation between the cGAS expression and BRCA1, SEI1, or PD‐L1 expression." (PMID 40135791, 2025). "Within the tumour microenvironment, Tregs secrete TGF‐β1, which inhibits the cyclic GMP‐AMP synthase–stimulator of interferon genes (cGAS–STING) pathway in myeloma cells." (PMID 40673641, 2025). "In multiple myeloma, Tregs promote TGF‐β1 production in tumour cells, which suppresses the cGAS–STING pathway and reduces MHC‐I expression while increasing PD‐L1 levels." (PMID 40673641, 2025). "qPCR analysis demonstrated that a dose‐dependent increase in the expression of cGAS and STING in myeloma cells treated with melphalan or bortezomib." (PMID 40135791, 2025). "Bortezomib has been reported to activate the cGAS/STING pathway and induce type 1 IFN production in multiple myeloma." (PMID 40459063, 2025). "qPCR analysis further confirmed the upregulation of cGAS in primary myeloma cells isolated from bone marrow aspirates of six myeloma patients treated with or without melphalan or bortezomib." (PMID 40135791, 2025). "In addition, analysis of public RNA‐seq datasets revealed a positive correlation between the expression of PD‐L1 and the expressions of cGAS and STING in primary myeloma cells." (PMID 40135791, 2025). "Finally, to assess the clinical relevance of chemotherapy and PD‐L1 expression in myeloma patients, qPCR analysis confirmed the upregulation of BRCA1, cGAS, SEI1, and PD‐L1 expressions in primary myeloma cells isolated from the bone marrow aspirates of 20 myeloma patients before and after treatment." (PMID 40135791, 2025). "After treatment of myeloma cells with chemotherapeutic drugs such as bortezomib or melphalan, DNA damage is induced, activating the cyclic guanosine monophosphate (GMP)‐adenosine monophosphate (AMP) synthase (cGAS)/stimulator of interferon genes (STING) signaling pathway." (PMID 40135791, 2025). "The predicted interaction of MB21D2 with Mab21‐nucleotidyltransferase enzymes, such as cGAS, and mitochondrial regulator, such as MIEF proteins, may further explain the clonal selection event, as fittest clone selection was previously observed in many cancers such as multiple myeloma." (PMID 32979859, 2020).
non-alcoholic fatty liver disease (9 papers, 2021 to 2025). "Mounting evidence has indicated that the abnormal activation of the cGAS-STING pathway is closely associated with the development of autoimmune diseases (AID), nonalcoholic fatty liver disease (NAFLD), chronic inflammation, Parkinson’s disease, and cardiovascular diseases." (PMID 40008133, 2025).